GSTP1 (glutathione S-transferase pi 1)
Diseases named in the same sentence as GSTP1 in open-access papers (continued):
Sharing a sentence is not in itself a finding about the gene and the disease.
ovarian carcinoma (continued). "MicroRNA-133b also targets GSTP1 expression to increase ovarian cancer cell sensitivity to chemotherapy drugs." (PMID 36422199, 2022). "Since LINC00152 silencing decreased the expression of MDRP1 as well as GSTP1, it is proposed as a potential novel therapeutic target related to downregulation of GSTP1 expression and ovarian cancer chemosensitising." (PMID 36422199, 2022). "They concluded that GSTP1 expression in tumor cells is related to drug resistance of patients with epithelial ovarian cancer." (PMID 33946704, 2021). "In Chinese ovarian cancer patients, positive correlations have been reported between the overexpression of GSTP1 and chemoresistance." (PMID 33946704, 2021). "Recently, treatment with micro RNA-133b-silenced GSTP1 with chemotherapy agent cisplatin or paclitaxel treatment reduced cell viability in epithelial ovarian cancer." (PMID 34209254, 2021). "Further, in the same group, the GSTP1-positive ovarian cancer patients showed shorter survival post-diagnosis than the GSTP1-negative cohort." (PMID 33946704, 2021). "Studies using in vitro models have demonstrated that GST superfamily members affect cell invasion; for example, downregulated GSTP1 influences chemosensitivity and inhibits invasion ability in cisplatin-resistant ovarian cancer cells." (PMID 34209254, 2021). "For example, high GSTP1 expression improved overall survival in epithelial ovarian cancer and maxillary sinus squamous cell carcinoma patients from China." (PMID 33946704, 2021). "GSTP1 is expressed at high levels in many human cancers, including colon, lung, breast, and ovarian cancers." (PMID 32526885, 2020). "Previous research has shown that GSTP1 is expressed at high levels in a variety of human cancers, including colon, lung, breast, and ovarian cancers." (PMID 32526885, 2020). "The reproductive female apparatus is subject to a variety of tumors; GSTP1-1 is also studied in correlation with women patients affected by cervix and ovarian cancer." (PMID 31357662, 2019). "Specifically in ovarian cancer, although with some controversy, several reports already associated high GSH levels or glutathione S-transferase P1 (GSTP1) activity with cisplatin or carboplatin resistance." (PMID 29949936, 2018). "Next, we compared the 5-year PFS (progression-free survival) and OS (overall survival) of advanced ovarian cancer patients between the GSTP1 rs1695 genotypes." (PMID 30038720, 2018). "Other studies showed reduced GSTP1 gene expression in prostate, endometrial, hepatocellular, and ovarian cancers." (PMID 30043549, 2018). "The significant effect for the third glutathione transferase under study, GSTP1, was noted only in the familial ovarian cancer group where the carriers of minor GG homozygote were at higher risk of developing cancer." (PMID 25591549, 2015). "The importance for glutathione S-transferase pi 1 (GSTP1) expression as a factor of bad prognosis and of poor response to chemotherapy has been reported in head and neck, gastric, colon, breast and ovarian cancers." (PMID 24342878, 2013). "GSTP1 plays a major role in the metabolism of cisplatin and carboplatin in ovarian cancer cells, and it may be used as a target gene and response biomarker for platinum-based chemotherapy." (PMID 39125992, 2024). "Interestingly, although there was an activation of NQO1 and other antioxidant enzymes such as SOD, GSTP1 and HO-1, in ovarian cancer cells treated with these compounds this antioxidant response was not sufficient to avoid cell death." (PMID 37175546, 2023). "This led to the conclusion that this is one more microRNA that might reduce ovarian cancer drug resistance by silencing the expression of the drug-resistance-related proteins, GSTP1 and MDR1." (PMID 36422199, 2022). "Another clinical study aimed to investigate the role of GSTP1 in primary epithelial ovarian cancer." (PMID 36422199, 2022). "For example, GSTP1’s role in chemoresistance is well established in human ovarian cancer." (PMID 33946704, 2021).
ovarian carcinoma (continued). "Besides, GSTP1 knockdown ovarian cancer cells showed heightened sensitivity (IC50) to cisplatin and carboplatin by 2.3- and 4.8-fold, respectively." (PMID 33946704, 2021). "The association between genetic polymorphisms of ERCC1, XRCC1 and GSTP1 with progression free survival (PFS) and overall survival (OS) in patients with epithelial ovarian cancer in varies ethnicities such as American, European or Asian were reported in several studies." (PMID 32711417, 2020). "Unfortunately, the studies carried out do not confirm an association between GSTP1 and epithelial ovarian cancer." (PMID 31357662, 2019). "For GSTP1, the G/G genotype seems to decrease the susceptibility to grade III neuropathy when compared to that in patients with A/G and/or A/A genotypes (recessive model of inheritance) in ovarian cancer." (PMID 30914949, 2019). "Furthermore, hypermethylation of other DNA damage repair pathway-related genes, like GSTP1, FANCF, and MGMT, has been described to be positively associated with chemosensitivity in ovarian cancer patients." (PMID 28641578, 2017). "In addition to ovarian cancer, GSTP1 is involved in the chemoresistance of other cancer types." (PMID 33946704, 2021). "Three studies well defined in ovarian cancer includes: Methylation of either BRCA1, GSTP1, or MGMT significantly correlates with improved response to chemotherapy (p = 0.013)." (PMID 31608277, 2019). "For the whole group of ovarian cancer patients the polymorphic variants in PGR, ABCB1, GSTT1, GSTM1 and GSTP1 genes did not change the risk of developing cancer." (PMID 25591549, 2015). "Concomitantly, GSTP1 mRNA levels in MCF-7_ADR were strongly increased when compared to MCF-7_wt, similar to the levels observed in each of the three completely unmethylated ovarian carcinoma cell lines." (PMID 20544021, 2010). "However, in ovarian cancer cells, stable GSTP1 knockdown did not significantly influence the IC50 value of doxorubicin." (PMID 33802702, 2021). "However, mRNA expression levels of MDR1 and GSTP1 and the protein expression levels of MDR1 and GSTP1 were downregulated following miR-130b transfection, which still suggested that miRNA-130b may be involved in the development of drug resistance in ovarian cancer cells." (PMID 36422199, 2022). "Therefore, we could speculate that functional SNPs located in PIK3CA and GSTP1 gene may disrupt transcription factor response elements, and further affect the expression level of PIK3CA and GSTP1 and ultimately affect the occurrence and development of ovarian cancer." (PMID 33273524, 2020).
hepatocellular carcinoma (35 papers, 2008 to 2025). A malignant tumor that arises from hepatocytes. "Evidence suggests that decreased expression of GSTP1 or CYP1A1 induced by polymorphisms at their respective gene loci has been associated with many liver diseases such as hepatocellular carcinoma." (PMID 25798582, 2015). "Other studies have also shown that the suppression of GSTP1 expression caused by promoter methylation contributes to the early stage of hepatocellular carcinoma." (PMID 25798582, 2015). "The association GSTP1 hepatocellular carcinoma indicates that it may function in the HCV life cycle." (PMID 26544179, 2015). "Numerous tumor types, including neuroblastoma, hepatocellular carcinoma (HCC), endometrial, breast, and prostate cancers, are regularly affected by GSTP1 methylation, which is frequently linked to tumor formation or a bad prognosis." (PMID 37901797, 2023). "It has been reported that the GSTP1 gene is hypermethylated in genotype 1b HCV core protein-positive cells and in hepatocellular carcinoma (HCC) tumors associated with HCV infection." (PMID 26544179, 2015). "Hypermethylation of the glutathione S-transferase π 1 (GSTP1) gene promoter region has been reported to be a potential biomarker to distinguish hepatocellular carcinoma (HCC) from other liver diseases." (PMID 22536438, 2012). "MBD2 has also been related to GSTP1 DNA methylation-dependent silencing in hepatocellular carcinoma." (PMID 18542062, 2008). "Additionally, p16, Ras association domain family 1 isoform A (RASSF1A), GSTP1, and Retinoblastoma protein-interacting zinc-finger gene 1 (RIZ1) are genes with aberrant methylation levels in HCV infections associated with hepatocellular carcinoma." (PMID 36560766, 2022). "This idea is in line with the markedly upregulated expression of GSTP1, primarily observed in HepG2 cells; the clinical significance of this parameter was repeatedly investigated in hepatocellular carcinoma and was found to correlate with a favorable prognosis." (PMID 34987311, 2021). "In addition, hepatocellular carcinoma patients carrying the GSTP1 Val/Val (rs1695GG) genotype had significantly better survival than those carrying the GSTP1 IIe/IIe (rs1695AA) genotype." (PMID 27281183, 2016). "Exogenous MOZ induced GSTP1 expression in rat hepatoma H4IIE cells." (PMID 25076909, 2014). "We assessed GST pi 1 (GSTP1) mRNA and protein levels in hepatocellular carcinoma (HCC) using genome databases and tissue microarray (TMA) technology." (PMID 29507666, 2018). "By using a cutoff value of β > 0.5, we identified five DME genes (CYP1B1, CYP8B1, GSTM2, GSTP1, and UGT3A2) that were regulated by DNA methylation in hepatoma cells." (PMID 26421064, 2015). "The CpG island of this gene becomes hypermethylated during the pathogenesis of human hepatocellular carcinoma and MBD2 appears bound to GSTP1 promoter region leading to gene silencing." (PMID 18542062, 2008). "Among these DME genes, the downregulation of CYP1B1, CYP8B1, GSTM2, GSTP1, UGT2B15, and UGT3A2 in hepatoma cells could be explained by DNA methylation status." (PMID 26421064, 2015). "GSTπ (GSTP1) is a member of the GST family and the hypermethylation GSTP1 CpG island DNA is detected in human hepatocellular carcinoma (HCC) tissues, which contributes to the negative expression of GSTP1 mRNA and protein." (PMID 23426146, 2013). "Glutathione S transferase 1 (GSTP1), is a detoxification enzyme and regulator of cell signaling in response to growth factors, hypoxia, stress, and other stimuli in human hepatocellular carcinoma (HCC) but its role in neutrophils is not clear." (PMID 30555831, 2018). "Although the GSTP1-1 enzyme is not expressed in human hepatocyte under physiological conditions, it may be present in some pathological conditions such as liver cirrhosis or hepatocellular carcinoma (HCC)." (PMID 31357662, 2019).
colon carcinoma (28 papers, 2011 to 2025). "The overall survival, GSTP1-1 expression, and GSTP1 genetic polymorphism in stage C of colon cancer were investigated in patients after resection alone versus patients after resection treated by a 5-fluorouracil-based chemotherapy." (PMID 31357662, 2019). "An association of GSTP1 with both acquired and intrinsic resistance to cisplatin was observed in human colon cancer cells." (PMID 26571237, 2015). "A 2015 study reported that mRNA and protein levels of GSTP1 in curcumin-treated groups were significantly lower than in control groups in human colon carcinoma cells." (PMID 35405942, 2022). "This same GSTP1, on the other hand, can be a tumor suppressor in the ApcMin/+ mouse model, in which the deletion of GSTP1 results in increased colon cancer incidence and tumor multiplicity." (PMID 35936694, 2022). "Several studies have found GSTP1 to be upregulated in colon cancer in comparison with normal colon tissue using immunohistochemistry and Western blotting." (PMID 34563043, 2021). "This study highlighted the possible predictive value of GSTP1-1 expression in regard to chemotherapy for stage C colon cancer." (PMID 31357662, 2019). "Specifically, GSTP1-1 levels are increased in ovarian, lung, breast, kidney, pancreas, and colon cancer, and lymphomas, and limit chemotherapy." (PMID 26043078, 2015). "There is ample evidence for this in humans where hypermethylation in the promoter region of GSTP1 results in reduced GSTP1 expression affecting hepatocellular, breast, renal, lung, and colon cancer, as well as some lymphomas." (PMID 23613737, 2013). "Overexpression of GSTP1 has been reported in various types of human tumors, including colon cancer, gastric cancer, esophageal cancer, and head and neck squamous carcinoma, and enhances human cancer cell chemoresistance." (PMID 21711528, 2011). "Given that GSTP1 is highly expressed in colon cancer cells and that elevated GSH levels can influence the efficacy of cytostatics, the increase in GSH and activation of detoxification pathways may support cellular defense mechanisms." (PMID 40649986, 2025). "Interestingly, GSTP1 is overexpressed in lung, ovary, pancreas, stomach, and colon cancers and this high expression level has been correlated with resistance to several anticancer drugs." (PMID 23094162, 2012). "Since cell lines have not been established from ACF tissues, we first investigated whether a colon cancer cell line (M7609) with appreciable GSTP1-1 activity could provide a clear fluorescence image following incubation with DNAT-Me and imaging using a confocal fluorescence microscope." (PMID 28747791, 2017). "Thus, this study aimed to investigate the effects of ISO on the mRNA expression of membrane transporters P-gp, BCRP, MRP 1, 2, and 5, the protein expression of P-gp, as well as the GSTP1 and GSH content in DLD1 and HCT-116 colon cancer cells." (PMID 40283931, 2025). "When colon cancer cells were treated with fermentation supernatants derived from raw and roasted pistachios, they displayed increased caspase-3 activity, decreased H2O2-induced DNA damage, and increased CAT, SOD2, and GSTP1 gene expression mRNA levels." (PMID 40699792, 2025). "Our research suggested that GSTP1 and PRDX6 might take part in the MDR of human colon carcinoma." (PMID 35509845, 2022). "Stage C colon cancer patients with high GSTP1-1 should be treated with 5-fluorouracil-based chemotherapy on the other hand patients with low intracellular concentrations of GSTP1-1 may not need to be treated." (PMID 31357662, 2019).
gastric cancer (27 papers, 2004 to 2026). A primary or metastatic malignant neoplasm involving the stomach. "In conclusion, we believe that this is the first study to evaluate the prognostic and predictive value of ERCC1 gene alteration, ERCC1 mRNA expression, and GSTP1 polymorphism in patients with unresectable or recurrent gastric cancer." (PMID 39516666, 2024). "Among the GST superfamily, GST alpha 1 (GSTA1), GST Mu 2 (GSTM2), and GST Pi 1 (GSTP1) have been found to be associated with cisplatin resistance in ovarian, lung, and gastric cancers." (PMID 37229486, 2023). "The I150V polymorphism of GSTP1 with a phenotype of reduced enzymatic capacity has been correlated with better therapeutic outcomes in gastric cancer patients receiving oxaliplatin‐based chemotherapy." (PMID 37229486, 2023). "Subjects with GSTP1 mutation had further additive risks for gastric cancer with smoking (OR = 1.64), alcohol (OR = 1.64) or H. pylori infection (OR = 3.7)." (PMID 32899442, 2020). "Regarding the interaction effect between dietary ORAC intake and GSTP1 rs1871042 polymorphism on gastric cancer risk, each dietary ORAC intake was divided into low and high groups based on the median level of the intake of controls." (PMID 33634021, 2020). "The risk of gastric cancer was higher in patients with the GSTP1 substitution mutation, showing that low levels of glutathione increased gastric cancer risk." (PMID 32899442, 2020). "GSTP1 polymorphism was significantly associated with gastric cancer suggesting that can be considered a risk factor associated with gastric carcinogenesis." (PMID 31357662, 2019). "In this study on the gastric cancer patients receiving oxaliplatin-based treatment, patients with GSTP1 p.Ile105Val A allele had a higher incidence of grade 3-4 cumulative neuropathy, gastrointestinal toxicity and hematological toxicity." (PMID 29507678, 2018). "Many studies showed that the polymorphic variants of GSTT1, GSTM1, and GSTP1 genes were associated with increased risk for gastric cancer, especially in the Asian population." (PMID 28182092, 2017). "In numerous studies the GSTM1, GSTT1, and GSTP1 gene polymorphisms have been investigated for their possible role in risk occurrence of various diseases, including gastric cancer." (PMID 28182092, 2017). "In contrast, GSTP1 rs1695 G allele with low GST level indicates an enhanced risk of chemoresistance to palliative chemotherapy in advanced gastric cancer." (PMID 25545243, 2014). "In the present case–control study, we reported that the polymorphism of GSTP1 was significantly associated with an increased risk of gastric cancer in the Chinese population." (PMID 23077566, 2012). "Genotype distribution of GSTP1 among atrophic gastritis and gastric cancer cases and superficial gastritis controls and association with gastric cancer risk." (PMID 23077566, 2012). "Interaction between GSTP1 Ile/Val polymorphism and H. pylori infection, smoking, and alcohol consumption in gastric cancer." (PMID 23077566, 2012). "Our analysis supports there being an elevated risk of gastric cancer among individuals with H. pylori infection, smoking, or alcohol consumption, and the GSTP1 Val/Val genotype." (PMID 23077566, 2012). "At present, there are few reports about the association between the polymorphisms of GSTP1 and the risk of gastric cancer." (PMID 23077566, 2012). "The GSTP1 Val allele shows an interaction with smoking, alcohol consumption, and especially H. pylori infection for increasing the risk of gastric cancer." (PMID 23077566, 2012). "The analysis showed a statistically significant 3.324-fold increase in gastric cancer risk associated with the GSTP1 allele Val." (PMID 23077566, 2012). "Association of the GSTP1 Val/Val genotype with H. pylori infection significantly increased gastric cancer and atrophic gastritis risk." (PMID 23077566, 2012).